REN (renin)
Diseases named in the same sentence as REN in open-access papers (continued):
Sharing a sentence is not in itself a finding about the gene and the disease.
Hypertension (continued). "Renin is the rate‐limiting step in the production of angiotensin II: a critical element in the regulation of blood pressure and in the pathogenesis of hypertension." (PMID 25524278, 2014). "Hypertension, particularly that induced by overstimulation of the renin-angiotensin system, possesses a large inflammatory component." (PMID 25505598, 2014). "For evaluation of genotype effect on the risk of hypertension, four SNPs were chosen: two SNPs (AGT and ACE) related to renin-angiotensin-aldosterone system and other two SNPs (ADM and CACNB2) newly identified in genome-wide association studies." (PMID 25313554, 2014). "In cases of suspected renin-mediated hypertension, the most physiological choice of antihypertensive treatment is the blockade of RAAS." (PMID 25177679, 2014). "In this paper, we describe the case of reninoma in an adolescent girl, who presented with a long history of headaches suggestive of renin-mediated hypertension." (PMID 25177679, 2014). "Early hypertension arises from the activation of the renin–angiotensin system (RAS), and compensatory LVH develops, which eventually leads to heart failure." (PMID 24622486, 2014). "We have shown in other studies that the renin–angiotensin system (RAS) plays a significant role in mediating the hypertension in both male and female SHR." (PMID 24844641, 2014). "As an excellent means of imaging of the renal vasculature, renal parenchyma, and adrenal glands, we recommended that CTA be considered in all cases of renin-mediated hypertension in children." (PMID 25177679, 2014). "The pathophysiological mechanism of hypertension is multifactorial and includes oxidative stress, inflammation, the renin-angiotensin system and autoimmune vascular dysfunction." (PMID 25501421, 2014). "We have also recently reported that the HMH-containing diets attenuated hypertension development in the SHR through reductions in plasma levels of renin and angiotensin converting enzymes." (PMID 25493943, 2014). "We investigated acute and chronic effects of CB1 cannabinoid receptor blockade in renin‐angiotensin system‐dependent hypertension using rimonabant (SR141716A), an orally active antagonist with central and peripheral actions." (PMID 25168868, 2014). "AGTRL1 and apelin are highly expressed in cardiovascular system, and they are believed to play an important role in counter-regulating the effect of renin-angiotensin system, a classical pathway leading to hypertension." (PMID 24465893, 2014). "Several mechanisms by which high sodium intake diets can promote the development of hypertension have been reported, including changes in vascular reactivity, the renin-angiotensin-aldosterone system, and sympathetic reflexes." (PMID 24941013, 2014). "Abatacept has been shown to effectively inhibit atherosclerosis in mice and to reduce renin-angiotensin-aldosterone (RAAS)-induced hypertension." (PMID 25238161, 2014). "We also discuss important points in the management of children presenting with renin-mediated hypertension." (PMID 25177679, 2014). "Db Ang-II mice developed hypertension comparable to that observed in db RAS mice despite lower plasma renin content." (PMID 24708836, 2014). "Alterations in the Swedish reimbursement system for the use of RAAS (renin–angiotensin–aldosterone system)-inhibiting drugs for hypertension in 2008 are an example." (PMID 25211055, 2014). "Patients with juxtaglomerular cell tumors often present hypertension, which is due to the secretion of renin." (PMID 25364414, 2014). "Hypertension is critically involved in the early stage of colorectal carcinogenesis via the activation of the renin-angiotensin system and subsequent induction of oxidative stress and chronic inflammation." (PMID 24959250, 2014). "As with the angiotensin-II infusion alone, db UNX + Ang-II mice developed similar level of hypertension with low plasma renin content." (PMID 24708836, 2014).
Hypertension (continued). "Administration of Ucn1 into animals reduced plasma concentrations of renin, AngII, and aldosterone, and inhibited hypertension-induced arterial remodeling (thickness)." (PMID 25462164, 2014). "The next step in diagnostic evaluation of hypertensive patients presenting with hypokalemia and metabolic alkalosis is the measurement of renin and aldosterone blood levels to confirm renin-mediated hypertension." (PMID 25177679, 2014). "Precursor mineralocorticoids probably contributed to hypertension, as suggested by elevated urinary metabolites and low aldosterone and renin levels observed in our patient." (PMID 25535576, 2014). "The current study describes, to the best of our knowledge, the first reported case of paraneoplastic secondary hypertension in a patient presenting with a renin-producing DSRCT." (PMID 25289084, 2014). "Renin-PRR signaling is essential for proper kidney development and is causally linked to hypertension." (PMID 24864188, 2014). "Diabetes is often accompanied by hypertension and they share conjunct pathways such as the Renin-angiotensin-aldosterone System, Sympathetic Nervous System, adipokines, inflammatory pathway, and oxidative stress." (PMID 25280459, 2014). "In 73 PA patients we evaluated anthropometric and biochemical parameters, renin-angiotensin-aldosterone system, calcium-phosphorus metabolism, and bone mineral density; control groups were 73 essential hypertension (EH) subjects and 40 healthy subjects." (PMID 24864141, 2014). "The ACTH test produces different aldosterone responses in patients with APA, IHA, and low-renin essential hypertension." (PMID 25239966, 2014). "It must be emphasized that in a minor study with men with hypertension it was found a strong association between SHBG and renin that can be another pathway for direct effects of SHBG on the control of blood pressure." (PMID 23594436, 2013). "The activity of the renin-angiotensin-aldosterone system (RAAS) is thought to be the major contributor to the pathogenesis of hypertension and its sequelae." (PMID 24223302, 2013). "The present study shows that majority of the intra-renal RAS components are suppressed in this model of low renin hypertension." (PMID 23840884, 2013). "Further studies are required to elucidate t role of renin-angiotensin system in adipocyte in relation to hypertension and stroke." (PMID 23876211, 2013). "To examine the potential role of the renin‐angiotensin system in hypertension in SHRcp, we compared the effect of azilsartan, a new ARB, on SHRcp with that on SHR and WKY." (PMID 23629805, 2013). "Increased circulating adipose factors like leptin and the renin–angiotensin system, which are classically shown to mediate obesity-induced hypertension in rabbits or classically salt-resistant rats, do not seem to play a role in our HFD model." (PMID 24400139, 2013). "The model also predicts that poor glycaemic control induced by diabetes contributes to hypertension by activating the renin angiotensin aystem." (PMID 24400038, 2013). "Our previous studies in male sheep showed that uni-x sheep had low renin hypertension, lower sodium excretion, albuminuria and 30% reduction in glomerular filtration rate (GFR) and renal blood flow (RBF) from 6 months of age compared to sham animals." (PMID 23840884, 2013). "Chronic exposure of rats to CIH results in elevation of plasma renin activity, and pharmacological inhibition of the renin-angiotensin-aldosterone system attenuates CIH-induced arterial hypertension." (PMID 23533685, 2013). "In many models of low renin hypertension, an up-regulation of the intra-renal renin-angiotensin system (RAS) has been reported to contribute to impaired renal function and maintenance of the systemic hypertension (for a review see." (PMID 23840884, 2013). "This conclusion is also supported by our findings, when we compare the UUO model with the hypertension-induced fibrosis in the animal model where renin is overexpressed." (PMID 23840546, 2013).
Hypertension (continued). "The plasma renin concentration is increased in obesity and contributes significantly to cardiovascular and renal complications (hypertension, atherosclerosis, coronary heart disease, and chronic kidney disease)." (PMID 24288524, 2013). "Lead has been found to be associated with kidney changes resulting in imbalance of the renin–angiotensin system, and also to alter calcium metabolism resulting in blood pressure elevation, a precursor to hypertension and cardiovascular diseases." (PMID 23603014, 2013). "The renin-angiotensin-aldosterone system (RAAS) plays a key role in the pathogenesis of cardiovascular disorders including hypertension and is one of the most important targets for drugs." (PMID 23404365, 2013). "PPARgamma was originally identified to stimulate the renin production during screening of the effect of free fatty acids on renin in an attempt to identify mechanisms responsible for the development of arterial hypertension during obesity." (PMID 24288524, 2013). "Hypertension is a consequence of increased renin substrate and sodium retention, facilitating the expansion of extracellular volume." (PMID 23533838, 2013). "Studies have suggested that the activity of the renin-angiotensin-aldosterone system play a major role in the target organ damage such as left ventricular hypertrophy occuring in hypertension." (PMID 24223302, 2013). "In this regard, new views have developed that expand the classical pathophysiology of patients of African ancestry to have low renin hypertension." (PMID 23721258, 2013). "Calcium channel blockers (CCB) and renin–angiotensin aldosterone system (RAAS) inhibitors are effective medicines for the treatment of hypertension." (PMID 23922924, 2013). "Activation of the RAAS has also been associated with hypertension, although RAAS-related pathways have been difficult to elucidate in humans with DM because of a phenomenon known as the “paradox of the low renin state in DM”." (PMID 23861950, 2013). "Progression of vascular disease is further enhanced by obesity and hypertension that up-regulate Nox-derived ROS, renin-angiotensin system and cytokine release, thus generating a continuous vicious circle." (PMID 23698776, 2013). "The renin-angiotensin system is a key regulator of cardiovascular function, and its activation is involved in the etiology of Mets, especially hypertension." (PMID 23860206, 2013). "Particularly since clinically the elevation in arterial pressure in low-renin hypertensives has been shown to be maintained by an inappropriately activated intra-renal RAS." (PMID 23840884, 2013). "As the first of a new class of orally-taken renin inhibitors, aliskiren was approved for the treatment of hypertension by the U.S. Food and Drug Administration in 2007, and proved to be effective in blood pressure control." (PMID 23922924, 2013). "Results with captopril corroborate many other previous works and further confirm the involvement of the renin-angiotensin system in the development of this model of arterial hypertension." (PMID 23368533, 2013). "Obesity is associated with insulin resistance, hyperinsulinemia, and activation of renin-angiotensin-aldosterone system, all of which contribute to systemic and intraglomerular hypertension, leading to structural glomerular damage." (PMID 25210651, 2013). "Although deletion of the NO-GC1 resulted in reduced vascular relaxation, the NO-GC1 KO mice develop hypertension only on the 129S6 background which displays higher activity of the renin-angiotensin-aldosterone system (RAAS) than other inbred mouse strains." (PMID 24260450, 2013). "The objective of the present study was to systemically examine the association between polymorphisms in the RAAS candidate genes (REN, AGT, ACE, AGTR, and CYP11B2) and hypertension." (PMID 24015270, 2013).
Hypertension (continued). "Although activation of the renin-angiotensin system in diabetes mellitus per se is associated with increased oxidative damage and cardiomyocyte apoptosis and necrosis in the diabetic heart, hypertension due to visceral adiposity may also influence diastolic function in T2DM." (PMID 23446214, 2013). "The mechanisms of hypertension in DM remain complex, such as stimulation of the sympathetic nervous system or activation of the renin-angiotensin system resulting in water-sodium retention." (PMID 23691167, 2013). "In our opinion, it is important to consider that these values relate to adults with hypertension, heart failure and other inflammatory secondary changes to the activity of the renin-angiotensin-aldosterone system." (PMID 24892616, 2013). "Recently, the E-boxes in the promoter regions of renin and angiotensinogen were shown to be direct targets of Usf1 and Usf2 and suggested to be involved in the pathogenesis of both hypertension and renal injury." (PMID 23653383, 2013). "In agreement, former studies showed that omega-3 PUFAs significantly decreased systemic arterial blood pressure in hypertension models of transgenic rats expressing the human renin and angiotensinogen genes and diabetic spontaneously hypertensive rats." (PMID 24303178, 2013). "Recently we reported that 2 year old uninephrectomised (uni-x) female sheep have low renin hypertension and reduced renal function." (PMID 23840884, 2013). "Specifically, rats transgenic for human renin and angiotensinogen develop early hypertension, cardiac hypertrophy, and renal damage, with marked albuminuria and focal cortical necrosis." (PMID 23902712, 2013). "In essential hypertension, the activation of the renin–angiotensin–aldosterone (RAS) system plays a pivotal role and angiotensin-converting enzyme (ACE) inhibitors or angiotensin receptor blockers (ARBs) are commonly used for treatment." (PMID 23203441, 2013). "Human and animal females are more susceptible to increased cortisol exposure in utero and subsequently develop hypertension in adulthood due to elevation of the renin-angiotensin system." (PMID 22830026, 2012). "Inflammation is recognized as an important factor in the pathophysiology of hypertension, with the renin-angiotensin-aldosterone system (RAAS) playing a key role in the disease." (PMID 22685633, 2012). "These in vivo studies provide support for the existence of renin or renin-like activity in the brain and its role in hypertension." (PMID 23316344, 2012). "In animals with concurrent hypercholesterolemia and activation of the endogenous renin-angiotensin system, the level of arterial hypertension was similar to that observed in normocholesterolemic wild-type C57 mice with high Ang II." (PMID 22330242, 2012). "It has long beenestablished that the two major contributors to systemic hypertension are theintrarenal renin-angiotensin system and chronic activation of the sympatheticnervous system." (PMID 22216059, 2012). "The renin – angiotensin system is involved both in the pathogenesis of hypertension, is modulated by numerous anti-hypertensive agents but is also a critical mediator of ischaemic injury in acute stroke." (PMID 22615742, 2012). "They successfully utilized a transperitoneal approach to perform bilateral nephrectomy for renin-mediated hypertension." (PMID 22802898, 2012). "We postulated that the renin-angiotensin system plays a dual role, contributing additively with ROS to DNA damage and additively with aging to arterial hypertension." (PMID 22330242, 2012). "In our and other laboratories, this issue has been addressed by activating the renin-angiotensin system through partial clipping (stenosis) of the left renal artery (known as two kidney-one clip, or 2K1C, hypertension) in young apoE-/- mice." (PMID 22330242, 2012).
Hypertension (continued). "Studies have shown that in some models of low renin hypertension the intrarenal renin angiotensin system is inappropriately activated, however, we have recently shown that at least in male uni-x sheep, renal renin and AngII levels were reduced." (PMID 22879965, 2012). "It is well known that the brain renin-angiotensin (RAS) system plays an essential role inthe development of hypertension, mainly through the modulation of autonomic activitiesand vasopressin release." (PMID 23316344, 2012). "eNO is now of interest in murine models of anaphylaxis, where chronic blockade of eNO increases expression of mRNA for renin, ACE, and AI receptors in the aorta, with the risk of hypertension." (PMID 23316249, 2012). "Mice lacking the vitamin D receptor or α-hydroxylase (required for vitamin D activation), constitutively over-express renin and develop hypertension." (PMID 22759247, 2012). "In another model, transgenic mice overexpressing renin developed hypertension-induced renal dysfunction." (PMID 22315658, 2012). "We recently reported that PRR knockdown in the brain attenuated Ang II-dependent hypertension in human renin and AGT double transgenic mice." (PMID 23316344, 2012). "Clinically, the renin–angiotensin–aldosterone system is activated in many disease states, including several forms of hypertension, heart failure, liver cirrhosis, and nephrotic syndrome." (PMID 22549242, 2012). "Overexpression of REN leads to hypertension via chronic overproduction of AngII, and inhibiting the regulators of the RAS--such as REN--is a common treatment for hypertension." (PMID 23282288, 2012). "Aldosterone, a specific mineralocorticoid receptor (MR) agonist and a key player in the development of hypertension, is synthesized as a final product of renin-angiotensin-aldosterone system." (PMID 23097668, 2012). "In rats, transgenic for both the human renin and angiotensinogen genes, hypertension and kidney damage developed which was largely independent of BP elevation but was dependent on an androgen component." (PMID 21603136, 2011). "Two displayed the full Liddle’s syndrome phenotype during pregnancy, with severe unprovoked hypokalaemia (K+ = 2.1 and 2.2 mmol/l), marked suppression of aldosterone and renin, and hypertension." (PMID 21107496, 2011). "COX-2 stimulates renin release, which plays a role in hypertension via the renin-angiotensin-aldosterone system." (PMID 21492462, 2011). "Hyperuricemia is suspected to influence the development of hypertension via its role in vascular endothelial cell dysfunction and activation of the renin-angiotensin system." (PMID 21294900, 2011). "The typical variant, which accounts for the majority of JGCT, has characteristically high renin concentration, hyperaldosteronism, hypokalemia and hypertension." (PMID 21871063, 2011). "Pgp appears to inhibit the efflux of aliskiren, a renin inhibitor used in the treatment of hypertension, in the small intestine." (PMID 23049672, 2011). "Renin has become an attractive target in controlling hypertension because of the high specificity towards its only substrate, angiotensinogen." (PMID 22372967, 2011). "Increased production of ROS in pathological situations such as hypertension and atherosclerosis is frequently mediated by activation of the renin-angiotensin system and NAD(P)H oxidase." (PMID 21251296, 2011). "In unilateral stenosis, the obstructed kidney responds as in bilateral stenosis with renin release, angiotensin II production and hypertension." (PMID 21251296, 2011). "We have very recently demonstrated, for the first time, that riociguat provides marked protection against cardiac and renal end-organ damage in experimental low-renin and high-renin models of hypertension." (PMID 21789188, 2011). "Antihypertensive agents should be treated for hypertension until accurate diagnosis is made, but blood pressure, plasma renin level usually normalize after the nephrectomy in most cases with JGCT." (PMID 21871063, 2011).